E2F1 (E2F transcription factor 1)
Diseases named in the same sentence as E2F1 in open-access papers (continued):
Sharing a sentence is not in itself a finding about the gene and the disease.
prostate carcinoma (continued). "Several TFs have been identified for regulating RRM2 transcription in different cancers, such as E2F1 in CRC, BRCA1 and E2F1 in glioblastoma, HPVE7 in cervical cancer, and FOXM1 in prostate cancer, and etc.." (PMID 34234118, 2021). "Collectively, these findings suggest that auranofin decreased E2F1 and AR3 expression and is a potent inhibitor of cell growth in double drug-resistant prostate cancer cells both in vitro and in vivo." (PMID 32354165, 2020). "E2F-1 has been reported to regulate PEG10 expression via directly binding to the promoter of PEG10 in liver and prostate cancer." (PMID 28193232, 2017). "Complex formation between E2F1 and HDAC1 was detected with immunoprecipitation in bladder and prostate cancer cells." (PMID 25816777, 2015). "Of the several transcription factors identified, a few namely E2F1, MYC, YY1, CHD1 and SMARCA4 which have been shown to express in prostate cancer tissues are of particular interest." (PMID 25938433, 2015). "Taken together, our data provided the evidence that E2F1 influences the ICAM-1 mediated anti-tumor microenvironment immune circuit through NF-κB modulation, which regulates prostate cancer cells escape from immune responses." (PMID 24742333, 2014). "However, it is unknown whether E2F1 affects ICAM-mediated immunity in prostate cancer." (PMID 24742333, 2014). "Elevated E2F1 protein expression correlated with increased E2F1 mRNA and increased expression of E2F1-target genes DHFR and PCNA, suggesting that E2F1 expression is elevated in advanced prostate cancer." (PMID 24742333, 2014). "Tumor xenograft mice model with E2F1 and ICAM-1-knockdown prostate cancer cells were used to investigate the effects of E2F1 and ICAM-1 on antitumor immunity." (PMID 24742333, 2014). "Such difference in xenografts developed from DU145/sh-E2F1 and DU145/sh-ICAM-1 cells demonstrated the opposing effects between E2F1 and ICAM-1 in tumorigenesis of prostate cancer." (PMID 24742333, 2014). "In prostate cancer CWR22-Rv1 and PC3 cell lines, which showed distinct δ-catenin overexpression, E2F1 and Hes1 expression pattern was altered." (PMID 21106062, 2010). "Similarly, in prostate cancer, SOAT1 inhibition by avasimibe suppresses tumor proliferation and metastasis via the E2F-1 signaling pathway." (PMID 40707931, 2025). "In the study, MUC1-C induced PBRM1 by E2F1-mediated activation at its promoters, allowing MUC1-C to form a complex with NRF2 and PBRM1 on the NRF2 target SLC7A11 to drive its transcription in human prostate cancer stem cells." (PMID 38358974, 2024). "Silencing E2F1 upregulated HSPB6 expression, promoting apoptosis in prostate cancer cells." (PMID 38374143, 2024). "MUC1-C (mucin 1 C terminal transmembrane subunit) could directly bind to E2F1, inducing the NOTCH1 signaling pathway and promoting NANOG expression, which in turn led to the promotion of CSCs stemness in prostate cancer stem cells." (PMID 36833320, 2023). "Considering that 3.92 μM is the maximum plasma lovastatin concentration detected in clinical trials, lovastatin alone seems unlikely to effectively modulate E2F1 in prostate cancer patients." (PMID 37960146, 2023). "In prostate cancer models, GAS5 could bind directly to transcription factor E2F1, enhancing the binding of E2F1 to the p27Kip1 promoter, and its transcription." (PMID 35456025, 2022). "Notably, AR, MYC and E2F1/2 are all established Hsp90 client proteins, and targeting Hsp90 inhibits expression of AR in prostate cancer, and MYC and E2F1 in other cancers." (PMID 35406480, 2022). "Meanwhile, regulating E2F1/E2F3/Caspase-3 axis may be one way that VA blocks stemness and advances apoptosis in prostate cancer cells." (PMID 36175803, 2022). "Consistent with this notion, depletion of E2F1 and E2F2 by RNA interference in the PC3 prostate cancer cell line significantly raised the percentage of Serine 139-phosphorylated histone H2AX (γH2AX)-positive cells, indicative of an increased DNA damage signaling." (PMID 36230876, 2022).
prostate carcinoma (continued). "We asked whether targeting E2F1 and E2F2 would affect cytotoxicity induced by these antimetabolites in prostate cancer cells." (PMID 36230876, 2022). "In prostate cancer, KRAS regulates ILK expression mediated by E2F1 in a KRAS-E2F1-ILK-hnRNP1 loop." (PMID 34233735, 2021). "In summary, this is a proof-of-principle study to demonstrate that simultaneously targeting E2F1 and AR3 via a combined therapy or a multi-targeting drug could circumvent castration resistance in prostate cancer." (PMID 32354165, 2020). "Furthermore, ENZ has been show to suppress the expression of the E2F1 target genes DHFR and TK1, and genes regulated by E2F1 were significantly enriched in an ENZ-resistant prostate cancer cell line." (PMID 32354165, 2020). "E2F1 knockdown by a specific short hairpin RNA (shRNA) or small interference RNA (siRNA) increased gene transcription and protein expression of ICAM-1 in human prostate cancer cells." (PMID 24742333, 2014). "It is possible that in individual human prostate cancer cases, simultaneously higher δ-catenin and E2F1 expression level during early cancer development is not beneficial for tumor growth." (PMID 21106062, 2010). "Thus, GR could have both indirect and direct crosstalk relationships with E2F1 in NEPC, like the interaction between FOXA1 and GR in AR-positive prostate cancer cells." (PMID 39027480, 2024). "To test the hypothesis that Hes1 is a negative regulator of δ-catenin expression, we co-transfected Hes1 expression vectors (pcDNA-flag-WT-Hes1 or pcDNA-flag-DN-Hes1) and E2F1, together with δ-catenin-luciferase reporter vectors BK1 or BK5, into CWR22-Rv1 or PC3 human prostate carcinoma cell lines." (PMID 21106062, 2010). "Recently, a possible mechanism has been reported that different modifications of E2F1 protein could activate different downstream genes thereby carrying out divergent functions in CRC, which was further verified by a report of a similar mechanism in prostate cancer." (PMID 38062013, 2023). "Consequently, E2F1, E2F4, and E2F5 had negative correlations with DBNDD1 expression in normal prostate tissues but positive correlations in prostate carcinoma tissues." (PMID 37569304, 2023). "Targeted knockdown of E2F1 did not affect expression and phosphorylation of NF-κB and IκBα, but facilitated NF-κB binding to the ICAM-1 promoter, subsequently induced ICAM-1 transcription and production in prostate carcinoma cells." (PMID 24742333, 2014). "These distinct roles of E2F1 in the presence and the absence of SETD6 might explain previous findings pointing toward a conflicting role of E2F1 in prostate cancer, because in the light of our findings the effects of E2F1 on tumor progression depend on the SETD6 expression level of the cancer cell." (PMID 41540805, 2026).
gastric cancer (107 papers, 2003 to 2026). A primary or metastatic malignant neoplasm involving the stomach. "In the study of glioma, SNHG5 promotes tumor growth by targeting E2F3, and E2F3 and E2F1 are both transcription factors of the E2Fs encoding gene family and are associated with poor prognosis of gastric cancer." (PMID 37258567, 2023). "We also analyzed the association between E2F1 expression and clinical characteristics in gastric cancer patients." (PMID 33986804, 2021). "KM plotter database demonstrated a close association between higher E2F1 expression level and worse overall survival of gastric cancer patients (p < 0.05)." (PMID 33986804, 2021). "The associations of these miRNAs and the E2F1 gene can serve as markers for the gastric cancer diagnosis." (PMID 33801990, 2021). "It promotes oxaliplatin-resistant gastric cancer cell invasion and proliferation by decreasing E2F transcription factor 1 (E2F1) and death-associated protein kinase 2 (DAPK2) expression." (PMID 32944391, 2020). "HOXA11-AS, associated with the cell cycle through E2F1, has been seen to promote gastric cancer proliferation and invasion (with EZH2) and can act as a “molecular sponge” for EZH2 by absorbing (via direct interaction) miR-1297." (PMID 29757368, 2018). "The close association between E2F1 and poor prognosis of patients suggests that E2F1 could serve as a prognostic biomarker and a therapeutic target in gastric cancer patients." (PMID 33986804, 2021). "Similarly, miR-135a has also been shown to potentiate oxaliplatin resistance of gastric cancer cells by down-regulating expression of E2F transcription factor 1 (E2F1) and death-associated protein kinase 2 (DAPK2)." (PMID 32192494, 2020). "In addition, E2F1 was a confirmed direct target of miR-331-3p in gastric cancer, and expression of E2F1 and other associated genes were able to predict invasive progression of bladder cancer." (PMID 29599914, 2018). "Furthermore, we found that levels of E2F1, 2, 3, 4, 5, and 7 mRNAs associated with gastric cancer cell invasion capacity, and has associated with tumor differentiation." (PMID 25646628, 2015). "Moreover, we found level of E2F1, 2, 3, 4, 5, and 7 mRNA associated with depth of gastric cancer invasion." (PMID 25646628, 2015). "In gastric cancer stem cells, E2F1 acts as a downstream transcription factor of circFAM73A/miR-490-3p/HMGA2 axis, contributing to maintain its stemness." (PMID 40886002, 2025). "Elevated E2F1 levels, suggested by qRT-PCR from both gastric cancer tissues and cell lines, pointed to E2F1’s possible oncogenic function." (PMID 39172101, 2024). "Our findings reveal that CDK5 promotes cell apoptosis by stabilizing DP1 and activating E2F1 signaling, suggesting its potential role in the prognosis and therapeutic decisions for patients with gastric cancer." (PMID 37990321, 2023). "Current study shows that E2F1 interacts with ARRDC1-AS1, so we infer that ARRDC1-AS1 has a similar function to SNHG5, and promotes the growth of gastric cancer cells by targeting E2F1." (PMID 37258567, 2023). "For example, lncRNA SUNO1 promotes cell cycle progression by controlling the YAP1/Hippo signaling pathway; miR-218 suppresses gastric cancer cell cycle progression via the CDK6/Cyclin D1/E2F1 axis." (PMID 37538116, 2023). "E2F1 is overexpressed in many cancers, including non-small cell lung cancer, gastric cancer, and papillary and anaplastic thyroid cancers." (PMID 36362068, 2022).
gastric cancer (continued). "Although the separate role of E2F1 or miR-532 in gastric cancer has been reported in previous studies, the new E2F1-miR-532 feedback loop was first found to explain the widespread increase of E2F1 and the decrease of miR-532 in gastric cancer." (PMID 35440106, 2022). "Altogether, these data strongly show that miR-532 inhibits gastric cancer cell proliferation, G1/S transition and promotes apoptosis and DNA damage by directly targeting E2F1." (PMID 35440106, 2022). "This study showed, for the first time, that CHPF is a potential prognostic indicator and tumor promoter in gastric cancer whose function is likely carried out through the regulation of E2F1." (PMID 34564711, 2021). "Lentivirus-mediated overexpression and downregulation of E2F1 were performed to evaluate the effect of E2F1 on the stemness properties of gastric cancer cells." (PMID 33986804, 2021). "E2F1 plays a significant role in gastric cancer progression by maintaining gastric cancer stemness properties through the regulation of stemness-associated genes." (PMID 33986804, 2021). "The effect of E2F1 on gastric cancer cell sensitivity of 5-Fu was evaluated using cell viability assay and TdT-mediated dUTP Nick-End Labeling staining." (PMID 33986804, 2021). "We found that E2F1 expression was significantly higher in gastric cancer tissues than in the paired adjacent normal tissues (p < 0.05) and was positively correlated with tumor size (p < 0.05), T stage (p < 0.05), and differentiation degree (p < 0.05)." (PMID 33986804, 2021). "For example, it was reported that the posttranscriptional regulation of the miR-106b-25 cluster by E2F1 promoted TGF-β resistance in gastric cancer." (PMID 34564711, 2021). "The transcription factor E2F1 is involved in the development of a number of oncological diseases, including gastric cancer." (PMID 33801990, 2021). "E2F1 enhanced 5-Fu resistance in gastric cancer cells, and the E2F1 expression level was correlated with the prognosis of gastric cancer patients receiving 5-Fu therapy." (PMID 33986804, 2021). "The high expression of E2F1 in gastric cancer cells and tissues was also revealed by qPCR and IHC analysis, respectively." (PMID 34564711, 2021). "For example, NNT-AS1 contributes to the tumorigenesis and progression of gastric cancer through targeting miR-424/E2F1." (PMID 32982585, 2020). "Forced over-expression of E2F1 enhances gastric cancer cells proliferation, while its silencing reduces cell proliferation through hindering cell cycle progression in these cells." (PMID 32695943, 2020). "In gastric cancer cells, after interference with the expression levels of eIF3b, E2F1, cyclin D and cyclin E was downregulated." (PMID 31423012, 2019). "GAS5 expression is also markedly downregulated in gastric cancer tissues and influences gastric cancer cell proliferation via regulating the expression of E2F1 and P21." (PMID 30853980, 2019). "Transfection of miR-331-3p in gastric cancer cells induced G0/G1 phase cell cycle arrest by attenuating the expression of its direct target E2F1, which is crucial for G1/S transition." (PMID 30228315, 2018). "In gastric cancer, miR-331-3p functions as key regulator in cell proliferation by leading to cell cycle arrest through directly suppression of E2F1 gene expression." (PMID 27548144, 2016). "Dysregulation of the miR-449/pRB-E2F1 regulatory loop therefore increases E2F1 activity and promotes cell cycle progression and inhibits apoptosis in gastric cancer." (PMID 27323780, 2016). "E2F family members play a major role during cell cycle G1/S transition in cells and the gene expression of E2F1, 2, 3, 4, 5, and 7 were all found to be overexpression (p < 0.01) in gastric cancer in this study." (PMID 25646628, 2015).
gastric cancer (continued). "Based on our data of stratified analysis, mRNA levels of E2F1 were also down-regulated in gastric cancer samples of patients with advanced stages." (PMID 26041881, 2015). "The intergenic region between ANRIL and p14ARF harbors a bidirectional promoter, which was reported to contain E2F binding sites and to be responsive to E2F1 in HeLa, A549 and gastric cancer cells." (PMID 29861427, 2015). "The miR-106b∼25 cluster is also upregulated by E2F1 that leads to TGFβ-resistance in gastric cancer." (PMID 26405162, 2015). "The ROC curves analysis showed that E2F1, 2, 3, 4, 5, and 7 can be the latent targets to distinguish gastric cancer tissue and the normal ones." (PMID 25646628, 2015). "The relationship between levels of miR-23b and Notch2 receptor, E2F1, and Ets1 mRNAs in the tumor samples from 21 gastric cancer patients was analyzed using the Pearson correlation analysis." (PMID 26041881, 2015). "Results also showed that N2IC down-regulated miR-23b expression in gastric cancer cells through up-regulating E2F1." (PMID 26041881, 2015). "For the treatment of gastric cancer, it is a potential application in combination therapies targeting miR-23b, E2F1, Notch2 receptor, and Ets1 in the future." (PMID 26041881, 2015). "The role of E2F1 in tumorigenesis is complicated and their expressions are higher in samples of gastric cancer patients with stages I–II but lower in those with stages III–IV." (PMID 26041881, 2015). "MiR-17 family clusters are emerging as key modulators of TGF-βtumor suppressor signaling in gastric cancer, through regulation of p21, E2F1–3 and E2F5 target gene expression." (PMID 25646628, 2015). "The SGC7901/DDP gastric cancer cell line stably overexpressing E2F1 exhibited significantly inhibited sensitivity to cisplatin, doxorubicin, and 5-fluorouracil." (PMID 25466554, 2014). "A cisplatin-resistant SGC7901/DDP gastric cancer cell line with stable overexpression of E2F1 was established." (PMID 25466554, 2014). "The results showed that the expression of E2F1 was significantly decreased and the expression of cyclin D1 was also downregulated in gastric cancer cells transfected with pCDNA3.1-GAS5 compared to those with empty vector." (PMID 24884417, 2014). "Recently, we showed that deregulated E2F1 acts as a driving force in gastric carcinoma progression and promotes tumor invasion and metastasis independently from its other cellular activities." (PMID 25466554, 2014). "This study investigated the possible involvement of E2F1 in anticancer drug resistance of gastric carcinoma in vitro and in vivo." (PMID 25466554, 2014). "Although this evidence implies that E2F1 is associated with carcinogenesis and development of MDR, the precise role of E2F1 in MDR of gastric carcinoma remains largely unexplored." (PMID 25466554, 2014). "We conclude that upregulation of E2F1 promotes the development of MDR in gastric carcinoma via inhibition of GAX gene expression, and increased expression of MDR1, MRP, and TAp73." (PMID 25466554, 2014). "To define the role of E2F1 in multidrug-resistant gastric carcinoma, we generated gastric carcinoma cells that stably express E2F1 and evaluated changes in IC50, the rate of doxorubicin efflux, cell cycle, and apoptosis." (PMID 25466554, 2014). "This indicates that E2F1 confers anticancer drug resistance by targeting ABC transporter family members in gastric carcinoma." (PMID 25466554, 2014). "In gastric cancer cells, E2F1 also appears to regulate miR-106b-25 expression in parallel with increases in MCM7 expression." (PMID 21283757, 2011). "Recently, silencing E2F-1 effectively inhibited gastric cancer progression by reducing cell proliferation and increasing apoptosis suggesting an oncogenic function." (PMID 20805990, 2010). "Furthermore, in gastric cancer, E2F1 was a potential downstream target of CHPF, and knockdown of E2F1 reduced the CHPF-induced promotion of gastric cancer." (PMID 40070576, 2025).